FAAH (fatty acid amide hydrolase)
Description:
Catalyzes the hydrolysis of endogenous amidated lipids like the sleep-inducing lipid oleamide ((9Z)-octadecenamide), the endocannabinoid anandamide (N-(5Z,8Z,11Z,14Z-eicosatetraenoyl)- ethanolamine), as well as other fatty amides, to their corresponding fatty acids, thereby regulating the signaling functions of these molecules. Hydrolyzes polyunsaturated substrate anandamide preferentially as compared to monounsaturated substrates. It can also catalyze the hydrolysis of the endocannabinoid 2-arachidonoylglycerol (2-(5Z,8Z,11Z,14Z-eicosatetraenoyl)-glycerol). FAAH cooperates with PM20D1 in the hydrolysis of amino acid-conjugated fatty acids such as N-fatty acyl glycine and N-fatty acyl-L-serine, thereby acting as a physiological regulator of specific subsets of intracellular, but not of extracellular, N-fatty acyl amino acids (By similarity).
Synonyms: FAAH1; FAAH-1; PSAB
Tractability: Small molecule: an approved drug acts on it; a high-quality ligand is known; it belongs to a druggable protein family. Antibody: UniProt predicts a signal peptide or a membrane-spanning region. PROTAC: ubiquitination databases record sites on it; its protein half-life has been measured; a small molecule that binds it is known.
Target class: Enzyme; Hydrolase
Chemical probes: CAY10499, OL-135 (high quality), PF-04457845 (high quality), PF-3845 (high quality), URB597
Safety:
Unwanted effects reported when the protein is acted on. In parentheses: how it was acted on, where the effect was seen, and who reports it.
adverse events (source: ClinPGx)
be tetrahydrocannabinol (THC) dependent (source: ClinPGx)
be THC dependent (source: ClinPGx)
post-operative nausea and vomiting (source: ClinPGx)
post-operative nausea and vomiting (PONV) (source: ClinPGx)
respiratory depression (source: ClinPGx)
weight gain (source: ClinPGx)
weight gain of more than 7% of baseline body weight (source: ClinPGx)
Gene: Protein-coding gene on chromosome 1 (46,394,265 to 46,415,754, forward strand). Ensembl gene ENSG00000117480.
Subcellular location: Endomembrane system; Cytoplasm, cytoskeleton
Subcellular location (Human Protein Atlas): Cytosol
Pathways (Reactome):
Metabolism: Arachidonate metabolism
Gene Ontology:
Molecular function: fatty acid amide hydrolase activity; protein binding; amidase activity; monoacylglycerol lipase activity; aminoacylase activity; carboxylesterase activity; hydrolase activity, acting on ester bonds; identical protein binding; lipid binding; N-(long-chain-acyl)ethanolamine deacylase activity; phospholipid binding
Biological process: fatty acid catabolic process; arachidonate metabolic process; monoacylglycerol catabolic process; fatty acid metabolic process; positive regulation of vasoconstriction; regulation of trans-synaptic signaling by endocannabinoid, modulating synaptic transmission; response to ethanol; response to immobilization stress
Cellular component: endoplasmic reticulum membrane; organelle membrane; cytoskeleton; endomembrane system; glutamatergic synapse; postsynapse; presynapse
Genetic constraint (gnomAD): Loss-of-function variants: 64 observed, 68.69 expected, observed/expected ratio (o/e) 0.93, 90% interval 0.76 to 1.15. The upper end of that interval is the gene's LOEUF score, 1.15, which puts it in group 5 of 6, group 1 being the genes least tolerant of losing a copy. Missense variants: 680 observed, 722.12 expected, observed/expected ratio (o/e) 0.94, 90% interval 0.88 to 1. Synonymous variants: 305 observed, 303.22 expected, observed/expected ratio (o/e) 1.01, 90% interval 0.92 to 1.11.
Homologues: Orthologues: chimpanzee FAAH (99% identical), macaque UQCRH (90% identical), rabbit FAAH (89% identical), dog FAAH (88% identical), guinea pig FAAH (85% identical), pig FAAH (85% identical), mouse Faah (83% identical), rat Faah (82% identical), tropical clawed frog faah.2 (53% identical), Caenorhabditis elegans faah-1 (36% identical), Caenorhabditis elegans faah-2 (33% identical), Caenorhabditis elegans faah-4 (30% identical), and 4 more. Paralogues in human: FAAH2 (21% identical), QRSL1 (16% identical).
Diseases named in the same sentence as FAAH in open-access papers:
FAAH is named in the same sentence as 224 diseases in open-access papers, as found by Europe PMC text mining. Sharing a sentence is not in itself a finding about the gene and the disease. The quoted sentences say what the papers report.
Anxiety (125 papers, 2011 to 2026). Intense feelings of nervousness, tension, or panic often arise in response to interpersonal stresses. "This pilot and exploratory study investigated DNA methylation and descriptive microRNA (miRNA) expression patterns of CNR1 and FAAH genes, and their associations with mood and anxiety outcomes, in trekkers exposed to Himalayan high altitude." (PMID 42192813, 2026). "For instance, in adolescents (12+ years), FAAH C385A was linked to lower anxiety and increased FA in the uncinate fasciculus – a frontolimbic pathway implicated in memory, cognitive control, and reward processing (Olson, Heide, Alm, & Vyas, 2015)." (PMID 40639419, 2025). "Another set of notable findings is that loss of FAAH from destabilization related to a single nucleotide polymorphism (rs324420) in humans is associated with reduced anxiety, and increased behaviors fostered by greater motivation." (PMID 40550956, 2025). "When compared to CC homozygotes, healthy individuals carrying the FAAH rs324420 A allele demonstrated enhanced fear extinction learning and lower anxiety levels." (PMID 37895295, 2023). "In a study with 928 Hungarian (all Caucasians) subjects (31.3 ± 10.5 years old; 69.8% females), FAAH C385A A allele carriers who experienced childhood adversities demonstrated higher levels of anxiety than CC carriers (p = 0.0023)." (PMID 37895295, 2023). "The authors concluded that reduced FAAH activity combined with childhood adversity were significantly associated with anxiety and depression in adulthood." (PMID 35563156, 2022). "Other FAAH variants were genetically linked with addiction, anxiety, eating disorders, depression, and obesity, emphasizing the endocannabinoid system’s importance for mental health but not specifically for ADHD." (PMID 34572359, 2021). "Behaviorally, these FAAH-mutated mice show decreased anxiety-like behavior and enhanced fear extinction learning." (PMID 33949949, 2021). "The A allele can therefore act as a human genetic model of FAAH inhibition associated with increased anandamide levels, and has been shown to protective against anxiety, stress and fear-related behaviour." (PMID 32398646, 2020). "Third, reduced FAAH activity in patients carrying the A allele of the FAAH rs324420 (C385A) polymorphism significantly increases the vulnerability to develop anxiety and depression when exposed to repetitive childhood trauma." (PMID 32395111, 2020). "In fact, genetically reduced FAAH activity in A allele carriers of FAAH rs324420 (C385A) polymorphism constitutes a risk factor to develop anxiety and depression in patients exposed to repetitive childhood trauma." (PMID 32395111, 2020). "Mutations in fatty acid amide hydrolase (FAAH) (C385A; rs324420) have been associated with alterations in fronto-amygdala function, which may be associated with anxiety and fear symptoms." (PMID 39920787, 2025). "As a result of a higher susceptibility to FAAH degradation, the SNP A allele may be associated with faster habituation of amygdala responsiveness to danger/threat, lower anxiety-like behaviour and greater fear-extinction learning." (PMID 37895295, 2023). "Conversely, this means that the inhibition of the enzyme FAAH could induce anxiolytic effects and may help treat depression, which is associated with increased anxiety." (PMID 37984468, 2023). "In this study, the R allele of R63Q and A allele of FAAH C385A were associated with higher depression and anxiety scores and could contribute to greater sensitivity to childhood trauma." (PMID 35563156, 2022). "Further, CBD inhibition of fatty acid amino hydrolase (FAAH), the primary degradation enzyme for the endocannabinoid, anandamide, is implicated or proposed to reduce compulsive behavior, anxiety, borderline personality disorder, and autism spectrum disorder." (PMID 34512286, 2021). "Similarly, an inhibitor of FAAH rescues anxiety phenotype, supporting the notion that eCB deficiency plays a pathophysiological role in the brain." (PMID 34950028, 2021).
Anxiety (continued). "In addition, allelic variants of the gene encoding FAAH have been involved in the regulation of anxiety-related behaviors." (PMID 32395111, 2020). "Furthermore, we have recently demonstrated that FAAH inhibition can prevent the unconditioned anxiety associated with acute 2-AG depletion." (PMID 30108473, 2018). "Previous studies demonstrated that FAAH inhibition results in marked reduction in nicotine self-administration and relapse to drug seeking, while here we demonstrated that the pharmacological inhibition of FAAH by URB597 decreased anxiety associated to protracted nicotine withdrawal." (PMID 22140525, 2011). "However, the direction of associations between FAAH, FA, and anxiety symptoms may vary by both tract and developmental stage." (PMID 40639419, 2025). "FAAH is the major catabolic enzyme for bioactive lipids involved in nociception, anxiety, and depression." (PMID 39855935, 2025). "FAAH polymorphisms that reduce enzymatic activity and elevate AEA levels have been associated with a lower risk for adolescent-onset anxiety in humans and mice and have been associated with a higher risk of PTSD in adolescents." (PMID 41001533, 2025). "Preclinical evidence suggests that inhibition of fatty acid amide hydrolase can alleviate pain‐ and anxiety‐related behaviors." (PMID 41395451, 2025). "The results of the presented experiments suggest that AEA participates in the modulation of emotional states and indicate the inhibition of FAAH as an innovative approach to anti-anxiety therapy." (PMID 40005177, 2025). "Next, we used inhibitors of FAAH (which breaks down AEA) or MAGL (which breaks down 2-AG) to assess which endocannabinoid is more responsible for anxiety-related behavior in mice." (PMID 40005177, 2025). "Preclinical literature has found that manipulations of both the CB1 receptor and FAAH can influence anxiety and fear extinction in males, but more recent evidence suggest that these manipulations produce incongruent or null effects in females." (PMID 40382500, 2025). "TLR3 mediated microglial activation and anxiety-like behaviors in female mice that were suppressed by the fatty-acid amide hydrolase 1 (FAAH) inhibitor URB597." (PMID 40558558, 2025). "Up to date, FAAH inhibitors have shown potential application in the treatment of chronic pain, anxiety, and inflammation." (PMID 39582223, 2025). "Anxiety induced by colitis was alleviated via the acute inhibition of FAAH in the CNS, suggesting that the decrease in AEA played a role in the development of anxiety." (PMID 38247868, 2024). "It is likely that bidirectional modulation of CNR2 and FAAH genes would likely increase social interaction and reduce anxiety and neuroinflammatory responses in autistic children." (PMID 38744725, 2024). "TNBS-induced colitis triggers anxiety and elevates circulating corticosterone, which is followed by the increased hydrolytic activity of the enzyme fatty acid amide hydrolase (FAAH), which breaks down the AEA in various corticolimbic brain regions." (PMID 38247868, 2024). "Both in vitro and in vivo studies support FAAH’s role in the protection against anxiety, depression, and inflammation without affecting cognition." (PMID 38543105, 2024). "This implies that blocking FAAH using either pharmacological or genetic methods can be more effective in reducing anxiety-related behaviours when dealing with challenging environmental conditions or after experiencing overt stressors." (PMID 39118031, 2024). "By regulating the neuronal excitability in the amygdala, a brain area that regulates anxiety, FAAH is thought to modulate anxiety-related behavior." (PMID 38542272, 2024). "Specifically, the pharmacological inhibition of FAAH enzyme activity prolongs the regulatory effects of the eCB system and reverses the stress-induced anxiety state in a cannabinoid receptor-dependent manner." (PMID 36983000, 2023).
Anxiety (continued). "The role of the CRF1 receptor was also demonstrated in another study that showed that, via CRF1R, CRF induces the enzyme fatty acid amide hydrolase (FAAH), which reduced endocannabinoid anandamide (AEA) in the amygdala, causing anxiety-like behavior." (PMID 36829752, 2023). "When we started to study the effects of the FAAH inhibitor URB-597 on anxiety, there was a wealth of literature on the issue, most of which reported positive findings." (PMID 37958761, 2023). "One study showed that similar effects can be obtained by invalidating the gene of the FAAH enzyme, whereas another showed that the overexpression of FAAH in the prefrontal cortex increased anxiety." (PMID 37958761, 2023). "A relatively new line of evidence suggests that FAAH inhibition goes beyond the amelioration of stress-induced anxiety by promoting a change in coping styles." (PMID 37958761, 2023). "The current neuroimaging study also lends support for the potential use of FAAH inhibitors to control amygdala hyperactivity, which is known to be involved in the pathophysiology of anxiety and trauma-related disorders." (PMID 37235067, 2022). "Considering that rs324420 FAAH polymorphism alters AEA levels affecting mood regulation and anxiety-like behaviors, another study evaluated the possible correlation between this polymorphism and self-reported anxiety in healthy adults." (PMID 35563156, 2022). "FAAH targets include endocannabinoid ligands which regulate pain, inflammation, and several cognitive and emotional states (e.g., anxiety, depression)." (PMID 35102242, 2022). "Authors showed that, as happens in preclinical studies, the increased activity of the FAAH enzyme decreased AEA concentrations in the basolateral AMY, inducing a loss of the inhibitory tone necessary for reducing anxiety and maintaining fear extinction." (PMID 35563156, 2022). "FAAH inhibition enhances fear extinction in healthy controls and reduces feelings of anxiety in people with social anxiety disorders." (PMID 37235067, 2022). "In line with that, in FAAH KO animals with elevated AEA levels a decreased anxiety phenotype was described." (PMID 35563822, 2022). "Preclinical research has provided overwhelming support for the use of FAAH inhibitors to facilitate the extinction of fear and attenuate anxiety." (PMID 34598785, 2022). "While a recent study in rats found inhibition of FAAH after a trauma inhibited the development of long-term symptoms of anxiety and fear, other studies have found high concentrations of AEA facilitate affective, negative memories of the trauma." (PMID 35105857, 2022). "Inhibition of FAAH with PF-3845 rescued the msP phenotype in several models of anxiety-like behavior, likely by restoring the integrity of stress-gating control in the CeA." (PMID 35655710, 2022). "For instance, a FAAH inhibitor (JNJ-42165279) has been recently tested in healthy males for the management of anxiety." (PMID 35799128, 2022). "Considering the effect of the FAAH rs324420 SNP on subjective experiences of anxiety, the present data are to be interpreted with care." (PMID 34893921, 2022). "Preclinical research consistently indicates that FAAH inhibition can enhance fear extinction and consolidation and suppress multiple aspects of the stress response, particularly, changes in anxiety and neuroendocrine function." (PMID 34598785, 2022). "This reduction in AEA signaling was mediated by central CRF-R1, and it contributed to the development of colitis-induced anxiety, as this was reversed by central inhibition of FAAH." (PMID 33452437, 2021). "Together, these data demonstrate that the induction of colitis results in a suppression of central AEA signaling via a CRF-R1 mediated increase in FAAH activity, which then promotes the development of anxiety." (PMID 33452437, 2021). "Intriguingly, increasing the levels of AEA by genetic deletion of FAAH or using pharmacological FAAH inhibitors (URB597) ameliorates anxiety-like behavior." (PMID 34093274, 2021).